CXCL10 (C-X-C motif chemokine ligand 10)
Diseases named in the same sentence as CXCL10 in open-access papers (continued):
Sharing a sentence is not in itself a finding about the gene and the disease.
coronary artery disease (24 papers, 2010 to 2025). "Higher CXCL10 levels were also found to be independently correlated with established laboratory risk markers of coronary heart disease such as acute-phase proteins and inflammatory cytokines." (PMID 30210493, 2018). "In a large case-control study of 312 patients with coronary heart disease and 472 controls, a significant association of increased serum CXCL10 was found with the risk of coronary heart disease." (PMID 30210493, 2018). "CXCL10 is an inflammatory chemokine which has been associated with risk of coronary heart disease and myocardial infarct size in the general population." (PMID 23365694, 2013). "The serum profiling reveals elevated values of IL-17A, IL-6, C-X-C motif chemokine ligand 10 (CXCL10) and higher values of markers associated with coronary artery disease." (PMID 33921718, 2021). "CXCL10 is the most extensively studied of the three chemokines in the clinical setting of ischemic heart disease; less is known about the role of CXCL9 and CXCL11." (PMID 30210493, 2018). "It would be interesting to analyze CXCL10 in samples of blood obtained by thrombus-aspiration during coronary artery percutaneous intervention (PCI) in patients with unstable coronary artery disease." (PMID 27795961, 2016). "Clinical studies provided important evidence for the role of CXCL10 in patients suffering from coronary artery disease (CAD)." (PMID 24868552, 2014). "In this scenario, it is of particular interest a clinical trial evaluating vitamin D repletion, inflammation, and CXCL10 (ClinicalTrial.gov NCT01570309) in coronary artery disease." (PMID 23690671, 2013). "Previous studies sought to correlate plasma CXCL10 levels with the occurrence of coronary heart disease (CHD)." (PMID 22164344, 2011). "Elevated levels of CXCL10/IP10 were also shown in sera of patients with coronary artery disease." (PMID 35268506, 2022). "A significant correlation was reported between the serum levels of CXCL10 and the severity of coronary artery disease, suggesting a potential role for CXCL10 in both angiogenesis and angiostasis; phenomena that occur during the development of collateral circulation." (PMID 34835155, 2021). "In addition, CXCL-10 is usually highly expressed in human atheroma during all stages of plaque formation, and serum CXCL-10 levels are correlated with coronary artery disease severity and occlusion of coronary arteries." (PMID 32410856, 2020). "While elevated serum CXCL10 was found to be significantly associated with increased risk of coronary heart disease, it was not an independent risk factor for future coronary events in population-based case-control studies." (PMID 30210493, 2018). "Circulating levels of CXCL10 are elevated in patients with coronary artery disease." (PMID 27795961, 2016). "Rothenbacher and colleagues demonstrated higher CXCL10 and CXCL8 and lower CCL5 levels in coronary heart disease patients compared with age- and gender-matched controls." (PMID 34835155, 2021). "A comparative study to evaluate the CXCL10, CCL20 and CCL22 levels in patients with ischemic heart disease." (PMID 30210493, 2018). "A significant correlation was found between elevated serum CXCL10 and CXCL12 levels and the severity of coronary artery occlusion in patients with coronary heart disease who underwent PTCA." (PMID 30210493, 2018). "Interestingly, most of these pro-inflammatory genes like CCL5, CXCL10, CXCL9, CTSK, and CD14 have been previously reported to be elevated in the serum of patients with coronary artery diseases." (PMID 35488341, 2022). "Independent studies have shown that the CXCL10/CXCR3 axis plays an extremely important immunomodulatory role in ischemic heart disease, myocarditis, leukoplakia, nonischemic heart failure, and KD, thus modulation of this axis is a potential immunotherapy target for these diseases." (PMID 33188570, 2021).
lymphoma (24 papers, 2009 to 2026). A malignant (clonal) proliferation of B- lymphocytes or T- lymphocytes which involves the lymph nodes, bone marrow and/or extranodal sites. "In xenograft models of lymphoma, squamous cell carcinoma, and lung adenocarcinoma, CXCL10 production negatively correlated with tumor growth and significantly reduced tumor-associated angiogenesis." (PMID 38957317, 2024). "We observed that CD20-TCB mediated lymphoma/T cell can trigger the production of IFNγ, which in turn leads to production of CXCL10." (PMID 33406104, 2021). "The results obtained in a mouse tumor model documenting a trend towards an enhanced NK cell recruitment into CXCL10-mucin-GPI treated lymphoma nodules suggested that the positive effects hold true also in vivo in a tumor setting." (PMID 24023642, 2013). "Since EBV+ lymphomas secrete high quantities of CCL3, CCL4, CCL22, and CXCL10 compared to EBV- lymphoma lines, the high expression of CCR5, CCR4, and CXCR3 on both EBV VST groups may indicate complementary/alternate axes of migratory mechanisms." (PMID 39011042, 2024). "In addition, LOAd703-infected lymphoma cells upregulated the secretion of several chemokines (CXCL10, CCL17, CCL22, CCL3, CCL4) essential for immune cell homing, leading to enhanced CAR T-cell migration." (PMID 33666760, 2021). "Consistent with the results of preclinical study, the contents of IL-1ra, IL-6, IL-8, CXCL10, MCP-1, and IFN-γ in serum of the response MM and lymphoma patients were increased after one week of PM treatment." (PMID 40562746, 2025). "Among them, over-expressed CCL18, CCL19, CXCL9, CXCL10, and CXCL13 were listed in the top 20 deregulated genes in all lymphoma datasets." (PMID 35452413, 2022). "In EBV-positive HL, the lymphoma microenvironment is T-reg cell rich and the transformed cells secrete immunosuppressive cytokines and chemokines like IL10, CCL5, CCL20, and CXCL10." (PMID 22979947, 2012). "In the field of HIV-NHL, early studies found significantly higher circulating CXCL10 levels in HAL patients compared to PLWH without lymphoma." (PMID 40723865, 2025). "All eight patients who were infected with N. mikurensis had N. mikurensis-specific, perforin-expressing Th1 and CD8+ T-cell populations with up-regulation of CXCL10 and IFN-γ, in contrast to the noninfected lymphoma patients who lacked these T-cell subsets." (PMID 41645598, 2026).
myocarditis (24 papers, 2011 to 2025). Myocarditis is a condition that is characterized by inflammation of the heart muscle (myocardium). "Recently, evidence was provided that polymorphisms in the CXCL9 and CXCL10 genes controlled the expression of chemokines in the myocardium and the degree of myocarditis in Chagas cardiomyopathy." (PMID 27795961, 2016). "Another pathology of concern may be linked to exposure to Spike protein and/or anti-COVID19 injections associated with CXCL10 production: myocarditis." (PMID 38549864, 2024). "Interferon-responsive CXCL9+/CXCL10+ macrophages have emerged as a conserved pro-inflammatory myeloid subset in diverse cardiac injuries, including immune checkpoint inhibitor myocarditis and viral myocarditis." (PMID 41412038, 2025). "CXCL10 is largely engaged in several cardiac and cardiovascular dysfunctions, such as atherogenesis and plaque formation, infarction, aneurysm, myocarditis, and cardiopulmonary bypass." (PMID 35712355, 2022). "Mice with a global deficiency of PAR1 expressed lower levels of CXCL10 and had increased Coxsackievirus B3 (CVB3)-induced myocarditis compared with control mice." (PMID 34253819, 2021). "In general, the role of CXCL10 in immune-mediated and autoimmune myocarditis is little studied; however, based on studies of infective myocarditis, a critical role for CXCL10 is likely." (PMID 27795961, 2016). "Results may indicate that genotypes associated to reduced risk in closely linked CXCL9 and CXCL10 genes may modulate local expression of the chemokines themselves, and simultaneously affect myocardial expression of other key chemokines as well as intensity of myocarditis." (PMID 23150742, 2012). "Furthermore, CXCL10 was shown to inhibit viral replication by recruiting natural killer cells in Coxsackievirus B3-induced myocarditis." (PMID 41154703, 2025). "While it has been shown that CXCL10 is higher in patients with CCC, and polymorphisms in CXCL9 and CXCL10 are responsible for their altered expression patterns, CXCR3 expression on CD8+ cells is inversely proportional to the intensity of myocarditis." (PMID 35794867, 2022). "Inflammatory processes and the resulting cytokine production can lead to the development of CXCL10-related pathologies, such as those described in the body of the text, namely, multisystem inflammation syndrome (MIS) and myocarditis, as well as autoimmune pathologies, such as bullous pemphigoid." (PMID 38549864, 2024). "Most tested patients (six of seven patients) had serum increases in the inflammatory cytokine interleukin (IL)-6 and in the chemokines CXCL9, CXCL10, and CXCL13, and the mass cytometry phenotypes of immune cell populations in the blood also showed correlations with myocardial inflammation." (PMID 34686542, 2021). "Also, CXCL10 and CCL5 were found to be among the dominant cytokines expressed in situ during acute experimental infection and chronic phase of T. cruzi-elicited myocarditis contributing to intense recruitment of activated T cells." (PMID 32393333, 2020). "CXCL10 is elevated in the heart following viral and nonviral infection and has the characteristics of a biomarker in rodent models of myocarditis." (PMID 27795961, 2016). "In their study, myocarditis was induced with Coxsackievirus B3 (CVB3), the primary cause of viral myocarditis, in mice that overexpressed a CXCL10 mutant protein without functional activity in order to antagonize endogenous CXCL10." (PMID 27795961, 2016). "Previous studies showed increased CXCL10/IP10 levels following both viral and nonviral myocarditis, suggesting that it could be a potential biomarker." (PMID 35268506, 2022). "CXCL10/IP10 was hypothesized to be a potential biomarker for myocarditis because of studies reporting the expression of CXCL10/IP10 in the heart following viral and nonviral infections." (PMID 35268506, 2022).
dementia (23 papers, 2007 to 2025). Loss of intellectual abilities interfering with an individual's social and occupational functions. "CXCL10 has also been reported to play a role in CNS neuronal injury, dementia, inhibition of angiogenesis, and interfere with VEGF function." (PMID 23630573, 2013). "We also note that CXCL10 is currently an experimental drug target for multiple autoimmune/inflammatory conditions, suggesting that the repurposing of these drugs to treat AD/dementia should be considered, particularly among individuals at risk for chronic inflammation." (PMID 36737481, 2023). "There is a growing appreciation of the role of CXCL10 in both infectious and non-infectious causes of central nervous system (CNS) neuronal injury, dementia, and inhibition of angiogenesis." (PMID 23630573, 2013). "The CSF of two HIV-ND patients also had elevated CXCL10, indicating that these patients had ongoing viral activity that could progress to dementia." (PMID 23078780, 2012). "In addition, there is growing evidence that IP-10/CXCL10 plays a role in both infectious and noninfectious causes of CNS neuronal injury, dementia, and inhibition of angiogenesis." (PMID 32801995, 2020). "With this purpose, CCL11/eotaxin, CXCL-10/IP-10, CCL2/MCP-1, and CCL4/MIP-1β levels were measured in the CSF of 87 PD patients (16 with dementia diagnosis) and 33 controls." (PMID 25386381, 2014).
Cognitive impairment (22 papers, 2013 to 2025). Abnormal cognition is characterized by deficits in thinking, reasoning, or remembering. "The chemokine CXCL10/IP-10 has also been associated with cognitive status in AD, the prototype cognitive disorder." (PMID 25386381, 2014). "While one of the proteins linked to EDII and incident cognitive impairment (CXCL10) has been nominated as a therapeutic target for AD, three candidate proteins (CCL2, CXCL10, and HGF) are therapeutic targets of ongoing clinical trials for non-neurologic disease." (PMID 36737481, 2023). "Interestingly, plasma CXCL10 levels have been linked to cognitive status in Parkinson's disease and are elevated in the cerebrospinal fluid of mild cognitive impaired patients." (PMID 29223680, 2018). "Consistent with our results, clinical research has shown a positive correlation between CXCL10 and cognitive impairment in AD patients." (PMID 37307824, 2024). "CXCL10 levels in cerebrospinal fluid (CSF) were higher in patients with AD and mild cognitive impairment, possibly based on caspase-dependent CXCL10-induced apoptosis of fetal neurons." (PMID 38931342, 2024). "CXCL10 is a chemokine found in high concentrations in AD, and cerebrospinal fluid CXCL10 concentrations have been positively correlated with cognitive impairment." (PMID 31461505, 2019). "Among the 52 inflammatory/immune proteins positively correlated with EDII score, six proteins (CXCL10, CCL3, HGF, OPG, CDCP1, NFATC3) were significantly associated with increased odds of incident cognitive impairment after adjusting for demographic characteristics and cardiovascular risk factors." (PMID 36737481, 2023). "Likewise, CXCL8 (interleukin 8) has been found to be increased in both the serum and CSF of AD patients, as well as CXCL10 (IP-10), whose levels in CSF correlated with AD cognitive impairment." (PMID 31766244, 2019). "Interestingly, cerebrospinal fluid levels of CXCL10 have been suggested to peak at the time of clinical mild cognitive impairment to AD conversion in humans." (PMID 29223680, 2018). "Prominently, we observed persistently elevated levels of eotaxin/CCL11, CCL2, CCL7, CXCL1, CXCL10 and BAFF in the DIPG, ALL, and aggressive osteosarcoma models, the same three models that also exhibit cognitive deficits." (PMID 38798554, 2024). "The study examined the interaction between five hub genes (Cxcl10, Gbp2, Cxcl12, Cxcr3, Ifih1) and four distinct immune cell types (M1 macrophages, NK resting cells, memory CD4 T cells, naive CD8 T cells) in mice brain tissues affected by cognitive impairment." (PMID 39286150, 2024). "Results provide insights into how inflammatory nutritional patterns are associated with an immune-related proteome and identify a group of proteins (CXCL10, CCL3, HGF, OPG, CDCP1, NFATC3, ITGA11) related to future cognitive impairment over a 14-year follow-up period." (PMID 36737481, 2023). "Chemokines CCL1, CCL2, CCL15, CCL27, CXCL9, CXCL10, and CX3CL1 might be most promising to serve as key molecular markers of cognitive impairment, although more cohort studies with larger populations are needed." (PMID 37291639, 2023). "Nonetheless, the same authors showed that serum levels of CXCL10/IP-10 were not increased in mild cognitive impairment and AD regardless of the stage of the disease." (PMID 25386381, 2014). "CSF CXCL10/IP-10 concentration was significantly increased in patients with mild cognitive impairment and mild AD in comparison with controls, but not in patients with severe AD." (PMID 25386381, 2014).
endothelial dysfunction (22 papers, 2010 to 2025). In vascular diseases, endothelial dysfunction is a systemic pathological state of the endothelium (the inner lining of blood vessels) and can be broadly defined as an imbalance between vasodilating and vasoconstricting substances produced by (or acting on) the endothelium. "The cytokine pattern observed in our oocyte-donation cohort—with increased IL-6, IL-1β, TNF-α, CXCL10, and VEGF—parallels these findings and supports the concept that immune activation and endothelial dysfunction are central to the disease process." (PMID 41561632, 2025). "Cytokines such as TNF-α, IL-6, IL-17A, CXCL9, CXCL10, and VCAM-1 are often elevated in both MASLD and SAH, playing crucial roles in immune cell recruitment, endothelial dysfunction, and fibrogenesis." (PMID 40977717, 2025). "Primary endothelial cells from human pulmonary arteries have shown evidence of endothelial dysfunction upon exposure to CXCL10, also known as interferon-induced protein-10 (IP-10)." (PMID 37637518, 2023). "Therefore, we hypothesize that after undergoing external stimulation, the secretion of CXCL10 by endothelial cells increases, leading to an increase in CXCL10/CXCR3 binding and exacerbating endothelial dysfunction, thereby exacerbating vascular occlusion." (PMID 40128669, 2025).
fibrosis (22 papers, 2012 to 2025). the formation of excess fibrous connective tissue in an organ or tissue in a reparative or reactive process. "While treatment with LXA4 reduced CXCL10 expression 2.39 times in comparison to fibrosis group, CXCR3 expression decreased 2.35 times." (PMID 35307625, 2022). "Both CXCL10 and IFNγ are increased in patients with MASLD and linked with development of steatohepatitis and fibrosis, which could partially explain their increased levels in septic patients." (PMID 40076848, 2025). "De Toma and Dierssen53 described the elevation of chemokines, specifically CXCL10, which,through stimulation of monocytes and IL-10, recruits fibrocytes and aids in theactivation of macrophages, facilitating lung damage such as fibrosis and leadsto a more severe manifestation of the disease." (PMID 37610949, 2023). "CXCL10 was involved in occurrence of renal fibrosis after high glucose stimulating in DN and restoring the abundance of CXCL10 could reduce the occurrence of fibrosis." (PMID 38617433, 2024). "Although the levels of IFN-inducible protein-10 (CXCL10/IP-10) and MIP1 were raised in mmp8-null mice with bleomycin-induced fibrosis, there were no significant variations in the amounts of functional TGF-β1 or IL-10." (PMID 35805895, 2022).